RNU6-534P (RNA, U6 small nuclear 534, pseudogene)
Gene: Small nuclear RNA gene on chromosome 7 (7,906,519 to 7,906,624, forward strand). Ensembl gene ENSG00000201747.
Homologues: Orthologues: chimpanzee U6 (98% identical), macaque U6 (89% identical), rat LOC120102607 (63% identical), mouse Gm26022 (58% identical). Paralogues in human: RNU6-1181P (77% identical), RNU6-480P (77% identical), RNU6-1031P (76% identical), RNU6-1209P (76% identical), RNU6-144P (76% identical), RNU6-16P (76% identical), RNU6-472P (76% identical), RNU6-1084P (75% identical), RNU6-1222P (75% identical), RNU6-1249P (75% identical), RNU6-433P (75% identical), RNU6-434P (75% identical), and 1287 more.